KARS1 (lysyl-tRNA synthetase 1)
Description:
Catalyzes the specific attachment of an amino acid to its cognate tRNA in a 2 step reaction: the amino acid (AA) is first activated by ATP to form AA-AMP and then transferred to the acceptor end of the tRNA. When secreted, acts as a signaling molecule that induces immune response through the activation of monocyte/macrophages. Catalyzes the synthesis of the signaling molecule diadenosine tetraphosphate (Ap4A), and thereby mediates disruption of the complex between HINT1 and MITF and the concomitant activation of MITF transcriptional activity. (Microbial infection) Interacts with HIV-1 virus GAG protein, facilitating the selective packaging of tRNA(3)(Lys), the primer for reverse transcription initiation.
Synonyms: KARS; KARS2; CMTRIB; DEAPLE; DFNB89; KRS; LEPID
Tractability: Small molecule: a structure with a bound ligand is known; a high-quality ligand is known; it has a high-quality binding pocket; it belongs to a druggable protein family. Antibody: UniProt places it where antibodies can reach, with high confidence; its Gene Ontology location is reachable by antibodies, with high confidence; the Human Protein Atlas places it where antibodies can reach. PROTAC: ubiquitination databases record sites on it; a small molecule that binds it is known.
Target class: Enzyme
Gene: Protein-coding gene on chromosome 16 (75,627,472 to 75,648,663, reverse strand). Ensembl gene ENSG00000065427.
Subcellular location: Cytoplasm, cytosol (Isoform Cytoplasmic); Cytoplasm; Nucleus; Cell membrane; Secreted; Mitochondrion (Isoform Mitochondrial)
Subcellular location (Human Protein Atlas): Cytosol; Plasma membrane
Pathways (Reactome):
Metabolism of proteins: Cytosolic tRNA aminoacylation; Mitochondrial tRNA aminoacylation
Developmental Biology: Transcriptional and post-translational regulation of MITF-M expression and activity
Metabolism: Selenoamino acid metabolism
Gene Ontology:
Molecular function: ATP:ADP adenylyltransferase activity; identical protein binding; lysine-tRNA ligase activity; protein binding; protein homodimerization activity; tRNA binding; amino acid binding; aminoacyl-tRNA ligase activity; ATP binding; nucleic acid binding; nucleotide binding; scaffold protein binding
Biological process: basophil activation involved in immune response; diadenosine tetraphosphate biosynthetic process; ERK1 and ERK2 cascade; lysyl-tRNA aminoacylation; positive regulation of DNA-templated transcription; positive regulation of inflammatory response to antigenic stimulus; positive regulation of macrophage activation; tRNA aminoacylation for protein translation; tRNA processing; response to X-ray
Cellular component: aminoacyl-tRNA synthetase multienzyme complex; cytoplasm; cytosol; extracellular region; mitochondrion; nucleus; plasma membrane; mitochondrial matrix; nucleoplasm
Genetic constraint (gnomAD): Loss-of-function variants: 37 observed, 55.15 expected, observed/expected ratio (o/e) 0.67, 90% interval 0.51 to 0.88. The upper end of that interval is the gene's LOEUF score, 0.88, which puts it in group 3 of 6, group 1 being the genes least tolerant of losing a copy. Missense variants: 705 observed, 671.25 expected, observed/expected ratio (o/e) 1.05, 90% interval 0.99 to 1.12. Synonymous variants: 280 observed, 239.48 expected, observed/expected ratio (o/e) 1.17, 90% interval 1.06 to 1.29.
Gene-disease validity (ClinGen):
ClinGen rates the evidence that KARS1 causes each of these diseases.
nonsyndromic genetic hearing loss (autosomal recessive): Limited.
Homologues: Orthologues: macaque KARS1 (96% identical), pig KARS1 (95% identical), chimpanzee KARS1 (94% identical), guinea pig KARS1 (92% identical), rabbit KARS1 (92% identical), dog KARS1 (92% identical), mouse Kars1 (90% identical), rat Kars1 (89% identical), tropical clawed frog kars1 (78% identical), zebrafish kars1 (78% identical), Drosophila melanogaster LysRS (66% identical), Caenorhabditis elegans kars-1 (56% identical). Paralogues in human: DARS2 (19% identical), DARS1 (18% identical), NARS1 (17% identical), NARS2 (15% identical).
Diseases named in the same sentence as KARS1 in open-access papers:
KARS1 is named in the same sentence as 97 diseases in open-access papers, as found by Europe PMC text mining. Sharing a sentence is not in itself a finding about the gene and the disease. The quoted sentences say what the papers report.
colon carcinoma (10 papers, 2015 to 2023). "The overexpressed membrane-bound KARS1 induces tumor cell migration for the progression of colon cancer." (PMID 32075312, 2020). "Overexpressed membrane-bound KARS1 and secreted KARS1 induce tumor cell migration and tumorigenic inflammation, respectively, for colon cancer progression." (PMID 32075312, 2020). "In colon cancer cells, KARS1 is secreted due to inflammatory stimuli." (PMID 32075312, 2020). "Levels of plasma lysyl-tRNA synthetase (KARS1), which was reported to be secreted from colon cancer cells by stimuli, along with other secreted aminoacyl-tRNA synthetases (ARSs), were analyzed in CRC and compared with the currently used biomarkers." (PMID 32075312, 2020).
colorectal cancer (7 papers, 2019 to 2024). A primary or metastatic malignant neoplasm that affects the colon or rectum. "The plasma AIMP1, KARS1, and IL-10 levels were significantly higher in the colorectal cancer patients than the healthy controls (p < 0.0001)." (PMID 32075312, 2020). "In addition, N-terminal cleavage of KARS1 occurs in colorectal cancer cell lines." (PMID 35501376, 2022).
HIV-1 infection (7 papers, 2012 to 2025). The type species of lentivirus and the etiologic agent of acquired immunodeficiency syndrome (AIDS). "KARS1 is released from the MSC upon HIV-1 infection, re-localizes to the nucleus, and is co-packaged with tRNALys in virions." (PMID 37296097, 2023).
hearing loss (5 papers, 2014 to 2025). "Over 50 pathogenic variants have been reported in KARS1, and most affected subjects have complex syndromes that can include hearing loss, peripheral neuropathy, optic neuropathy, cardiomyopathy and leukoencephalopathy." (PMID 39062730, 2024). "We detected two missense KARS1 variants in a compound heterozygous state in one patient with hearing loss." (PMID 34062854, 2021). "Variants in the KARS1 gene cause neurological disorders other than hearing loss." (PMID 34062854, 2021). "Dysfunction of some mitochondrial aminoacyl-tRNA synthetases (encoded by the KARS1, HARS2, LARS2 and NARS2 genes) results in a great variety of phenotypes ranging from non-syndromic hearing impairment (NSHI) to very complex syndromes, with a predominance of neurological signs." (PMID 39062730, 2024).
Leukoencephalopathy (5 papers, 2018 to 2025). This term describes abnormality of the white matter of the cerebrum resulting from damage to the myelin sheaths of nerve cells. "Mutations in KARS1 are associated with a wide range of clinical phenotypes, including leukoencephalopathy, hereditary deafness, peripheral neuropathies, and multisystemic involvement." (PMID 41002930, 2025). "Biallelic pathogenic variants in KARS1 can result in NSHI (DFNB89 type), or in HI associated with leukoencephalopathy and other clinical signs." (PMID 39062730, 2024).
microcephaly (5 papers, 2018 to 2025). A congenital or acquired developmental disorder in which the circumference of the head is smaller than normal for the person's age and sex. "In conclusion, KARS1‐related disorder is a multi‐system mitochondrial disease with congenital progressive microcephaly and cerebral tissue loss, white matter anomalies, epilepsy, oculomotor dysfunction, and immune‐hematological dysfunctions." (PMID 33942428, 2021). "Severe microcephaly has already been described in individuals with bi‐allelic KARS1 pathogenic variants, but we found that the microcephaly and signs of cerebral tissue loss (including thinning of corpus callosum) are progressive, suggesting neurodegeneration." (PMID 33942428, 2021). "Congenital progressive microcephaly, oculo‐motor dysfunction, and immuno‐hematological problems are emerging phenotypes in KARS1‐related disorder." (PMID 33942428, 2021).
Charcot-Marie-Tooth disease (4 papers, 2014 to 2023). An inherited degenerative disorder involving the peripheral nerves. "The most common condition, the Charcot-Marie-Tooth disease (CMT), is associated with dominant, monoallelic mutations in six aaRSs genes (e.g.,YARS1, MARS1, KARS1, WARS1, AARS1, GARS1, and HARS1)." (PMID 37495112, 2023).
leukodystrophy (3 papers, 2018 to 2021). Leukodystrophies are a group of rare, progressive, metabolic, genetic diseases that affect the brain, spinal cord and often the peripheral nerves. "Bi‐allelic pathogenic variants in KARS1 have been associated to sensorineural hearing and visual loss, neuropathy, seizures, and leukodystrophy." (PMID 33942428, 2021).
melanoma (3 papers, 2020 to 2023). A malignant, usually aggressive tumor composed of atypical, neoplastic melanocytes. "We highlight how MITF, by controlling differentiation and genome integrity, may regulate melanoma-specific antigen expression by interfering with the endolysosomal pathway, KARS1, and antigen processing and presentation." (PMID 33276788, 2020).
Cerebral atrophy (2 papers, 2021 to 2025). Atrophy (wasting, decrease in size of cells or tissue) affecting the cerebrum. "Cerebral atrophy, often associated with diffuse ventriculomegaly, has been consistently linked to KARS1 mutations." (PMID 41002930, 2025). "In our series, neuroimaging studies showed that KARS1 pathogenic variants can result in a wide range of anomalies including white matter signal changes and severe cerebral atrophy with thinning of corpus callosum." (PMID 33942428, 2021). "The combination of cerebral and spinal calcifications with progressive cerebral atrophy and ventriculomegaly should be regarded as a key diagnostic indicator, raising suspicion for aminoacyl-tRNA-synthetase-related disorders, particularly those involving KARS1 mutations." (PMID 41002930, 2025).
epilepsy (2 papers, 2021 to 2025). A brain disorder characterized by episodes of abnormally increased neuronal discharge resulting in transient episodes of sensory or motor neurological dysfunction, or psychic dysfunction. "Epilepsy, often drug-resistant, has been described in 37 individuals with KARS1-related syndrome so far, presenting with heterogeneous phenotypes including epileptic encephalopathies." (PMID 41002930, 2025).
liver cancer (2 papers, 2021). An epithelial or non-epithelial malignant neoplasm that arises from the liver. "To study the functionality of KARS in liver cancer cells, we first examined KARS1 expression at mRNA and protein levels, and tRNA‐Lys‐CUU expression across eight HCC cell lines." (PMID 33084231, 2021). "Altogether, these associations between the expression levels of tRNA‐Lys‐CUU and KARS1 in tumour tissues and prognosis of HCC patients indicate a potential clinical relevance for the interface of charging lysine with its tRNA in liver cancer." (PMID 33084231, 2021).
Atrophy (1 paper, 2025). Any weakening or degeneration, especially through lack of use. "Neuroimaging findings in our patient were predominantly characterized by cerebral and cerebellar calcifications, along with progressive severe atrophy and ventriculomegaly, both features frequently reported in individuals with KARS1 mutations." (PMID 41002930, 2025).
colitis (1 paper, 2020). Inflammation of the colon. "As KARS1 is secreted during inflammation and CRC is highly associated with inflammation, plasma KARS1 was investigated using the colitis-induced CRC mouse model, azoxymethane (AOM)/dextran sodium sulfate (DSS)." (PMID 32075312, 2020). "Based on this, we analyzed the plasma levels of KARS1 in human CRC samples and in a colitis-induced CRC mouse model." (PMID 32075312, 2020).
head and neck squamous cell carcinoma (1 paper, 2025). A squamous cell carcinoma that arises from any of the following anatomic sites: lip and oral cavity, nasal cavity, paranasal sinuses, pharynx, larynx, and salivary glands. "Lysyl-tRNA synthetase (KARS1) gene codes for protein KRS that is a prognostic marker in head and neck squamous cell carcinoma, lung adenocarcinoma kidney, renal clear cell carcinoma, and a novel post-operative monitoring and diagnostic biomarker for CRC." (PMID 40867231, 2025).
inflammatory bowel disease (1 paper, 2020). A spectrum of small and large bowel inflammatory diseases of unknown etiology. "Although the mechanism behind high plasma KARS1 levels during the pathogenesis of CRC is not clear, it might have diagnostic potential for inflammatory bowel disease (IBD)-derived CRC." (PMID 32075312, 2020).
prostate carcinoma (1 paper, 2022). A carcinoma that arises from epithelial cells of the prostate gland. "GARS1 and KARS1 display androgen-dependent transcriptional initiation in several hormone-responsive cells, such as prostate cancer cells 19; thus, transcription of GARS1 and KARS1 is initiated in cancers with increases in AREs." (PMID 35501376, 2022).
cancer (28 papers, 2013 to 2025). A tumor composed of atypical neoplastic, often pleomorphic cells that invade other tissues. "The disruption of ARSs, including DARS1, IARS1, and KARS1, has been associated with cancer progression." (PMID 40867231, 2025). "KARS1 is phosphorylated at two distinct residues in response to different signals and modulates cancer-associated characteristics." (PMID 35501376, 2022). "Among the ARSs, unique behaviors of lysyl-tRNA synthetase 1 (KARS1) has been strongly associated with cancer." (PMID 32075312, 2020). "Compared with KARS1, GARS1 predominantly features gene amplification in cancers, whereas KARS1 features more deletions and mutations than amplifications." (PMID 33266490, 2020). "EPRS1, methionyl-tRNA synthetase 1 and lysyl-tRNA synthetase 1 also play essential roles in the progression and metastasis of cancer cells by regulating different signals." (PMID 36675119, 2023). "Serum starvation triggers N-terminal truncation of KARS1 via activated caspase-8, leading to exosome-mediated secretion from cancer cells for proinflammatory activities." (PMID 35501376, 2022). "Truncated KARS1 interacts with the syntenin–syndecan complex and is secreted via exosomes from cancer cells." (PMID 32075312, 2020). "Whereas membrane KARS1 has been found to regulate tumor migration, secreted KARS1 exhibits proinflammatory functions in the cancer microenvironment." (PMID 32075312, 2020). "The cancer specificity and burden correlation of plasma KARS1 level were validated using azoxymethane (AOM)/dextran sodium sulfate (DSS) model, and paired pre- and post-surgery CRC patient plasma." (PMID 32075312, 2020). "Based on the plasma level and its correlation with the cancer burden in CRC, we found that the diagnostic potential of KARS1 was better than that of CEA and CA19-9." (PMID 32075312, 2020). "For instance, TNF-α induces secretion of KARS1 from cancer cells to the extracellular space." (PMID 35501376, 2022). "KARS1 stabilizes 67LR, leading to increased cell migration and cancer metastasis." (PMID 35501376, 2022). "Furthermore, chemical intervention of interaction between KARS1 and 67LR in the cell membrane is effective against cancer metastasis." (PMID 35501376, 2022). "Higher GARS1 mRNA levels correspond to significantly worse survival in five different cancer types (BLCA, KIRC, LGG, LIHC, and LUAD) compared to only one for KARS1 (HNSC)." (PMID 33266490, 2020).
tumor (20 papers, 2012 to 2025). "Our data shows that the level of Plasma KARS1 reflects the tumor size in CRC patients and significantly associated with CRC." (PMID 32075312, 2020). "We found that mRNA expression levels of KARS1 were significantly higher in HCC tumour tissues compared with paired TFL tissues (n = 59), and this was further confirmed by analysis of the publically available GEPIA database." (PMID 33084231, 2021). "Importantly, similar to what we found in HCC patients, KARS1 expression was significantly higher in patient CC tumour tissues based on the GEPIA database." (PMID 33084231, 2021). "Since plasma KARS1 level was correlated with tumor size of CRC, we investigated whether plasma KARS1 could be used as a monitoring biomarker." (PMID 32075312, 2020). "In addition, we found a significant positive correlation of tRNA‐Lys‐CUU and KARS1 in tumour tissues, but not in healthy liver tissues or TFL tissues." (PMID 33084231, 2021).
mitochondrial disease (2 papers, 2018 to 2021). "Pendular nystagmus, ophthalmoplegia, jerky eye movements are typical clinical signs of mitochondrial diseases and have been reported in individuals with KARS1 defects." (PMID 33942428, 2021).
KARS1 also shares sentences with these, for which no sentence is quoted: malaria (8 papers); peripheral neuropathy (6); infection (5); lung carcinoma (5); breast carcinoma (4); deafness (4); pancreatic cancer (4); cardiomyopathy (3); developmental delay (3); gastric cancer (3); lactic acidosis (3); neurologic disorders (3); neuropathy (3); non-small cell lung carcinoma (3); anaphylaxis (2); Hearing impairment (2); leprosy (2); myopathy (2); parasite infection (2); Perrault syndrome (2); acoustic neuroma (1); adenocarcinoma (1); adenoma (1); Ataxia (1); breast tumors (1); cataract (1); cerebral palsy (1); cervical cancer (1); Charcot-Marie-Tooth neuropathy (1); colorectal tumors (1).
A further 47 diseases each share a sentence with KARS1 in 1 paper.